CHST3 (carbohydrate sulfotransferase 3)
Description:
Sulfotransferase that utilizes 3'-phospho-5'-adenylyl sulfate (PAPS) as sulfonate donor to catalyze the transfer of sulfate to position 6 of the N-acetylgalactosamine (GalNAc) residue of chondroitin. Chondroitin sulfate constitutes the predominant proteoglycan present in cartilage and is distributed on the surfaces of many cells and extracellular matrices. Catalyzes with a lower efficiency the sulfation of Gal residues of keratan sulfate, another glycosaminoglycan. Can also catalyze the sulfation of the Gal residues in sialyl N-acetyllactosamine (sialyl LacNAc) oligosaccharides (By similarity). May play a role in the maintenance of naive T-lymphocytes in the spleen (By similarity).
Synonyms: C6ST; C6ST1; HSD
Tractability: Antibody: UniProt predicts a signal peptide or a membrane-spanning region. PROTAC: ubiquitination databases record sites on it.
Safety:
Unwanted effects reported when the protein is acted on. In parentheses: how it was acted on, where the effect was seen, and who reports it.
chance of response (source: ClinPGx)
chance of response to treatment (source: ClinPGx)
drug toxicity (source: ClinPGx)
Gene: Protein-coding gene on chromosome 10 (71,964,395 to 72,013,558, forward strand). Ensembl gene ENSG00000122863.
Subcellular location: Golgi apparatus membrane
Subcellular location (Human Protein Atlas): Cytosol; Golgi apparatus
Pathways (Reactome):
Metabolism: CS-GAG biosynthesis; Keratan sulfate biosynthesis
Disease: Defective CHST3 causes SEDCJD
Gene Ontology:
Molecular function: chondroitin 6-sulfotransferase activity; keratan sulfotransferase activity; N-acetylglucosamine 6-O-sulfotransferase activity; proteoglycan sulfotransferase activity; sulfotransferase activity
Biological process: chondroitin sulfate proteoglycan biosynthetic process; sulfur compound metabolic process; keratan sulfate proteoglycan biosynthetic process; N-acetylglucosamine metabolic process; carbohydrate metabolic process
Cellular component: Golgi membrane; Golgi apparatus
Genetic constraint (gnomAD): Loss-of-function variants: 20 observed, 25.97 expected, observed/expected ratio (o/e) 0.77, 90% interval 0.54 to 1.12. The synonymous counts are far from expectation, so gnomAD's model fits this gene poorly and the ratio says little. Missense variants: 693 observed, 625.74 expected, observed/expected ratio (o/e) 1.11, 90% interval 1.04 to 1.18. Synonymous variants: 334 observed, 274.98 expected, observed/expected ratio (o/e) 1.21, 90% interval 1.11 to 1.33.
Gene-disease validity (ClinGen):
ClinGen rates the evidence that CHST3 causes each of these diseases.
spondyloepiphyseal dysplasia with congenital joint dislocations (autosomal recessive): Definitive.
Homologues: Orthologues: chimpanzee CHST3 (100% identical), macaque CHST3 (98% identical), rabbit CHST3 (90% identical), dog CHST3 (90% identical), pig CHST3 (88% identical), guinea pig CHST3 (88% identical), rat Chst3 (86% identical), mouse Chst3 (85% identical), tropical clawed frog chst3 (71% identical), zebrafish chst3a (48% identical), Drosophila melanogaster CG31637 (19% identical), Drosophila melanogaster CG9550 (15% identical). Paralogues in human: CHST1 (35% identical), CHST6 (27% identical), CHST5 (26% identical), CHST4 (24% identical), CHST7 (24% identical), CHST2 (23% identical).
Diseases named in the same sentence as CHST3 in open-access papers:
CHST3 is named in the same sentence as 47 diseases in open-access papers, as found by Europe PMC text mining. Sharing a sentence is not in itself a finding about the gene and the disease. The quoted sentences say what the papers report.
spondyloepiphyseal dysplasia (10 papers, 2012 to 2023). An osteochondrodysplasia that results in abnormalities of bone growth in the vertebral column and the epiphysis. "Some spondyloepiphyseal dysplasia patients harboring CHST3 variants have also demonstrated multiple heart valve deformities." (PMID 36042462, 2022). "Patients with variants in CHST3 were initially diagnosed with Larsen syndrome, chondrodysplasia with multiple dislocations or spondyloepiphyseal dysplasia." (PMID 36042462, 2022). "Deficiency of carbohydrate sulfotransferase 3 has been reported in a small number of patients with recessively inherited spondyloepiphyseal dysplasia with joint dislocation, short stature and scoliosis." (PMID 36042462, 2022). "Mutations in CHST3 have been previously reported to be associated with a rare phenotype of skeleton dysplasia, known as Spondyloepiphyseal dysplasia." (PMID 30200136, 2018). "Mutations in the CHST3 gene have been previously found as associated with spondyloepiphyseal dysplasia in humans, which is a congenital skeletal development disorder characterized by joint dislocations, included hip dislocation." (PMID 25874693, 2015). "DD has overlapping features with spondyloepiphyseal dysplasia with congenital joint dislocations (SDCD) due to Carbohydrate (chondroitin 6) Sulfotransferase 3 (CHST3) mutations." (PMID 22539336, 2012). "Gene mutation analysis of CHST3, CHST6 and CHST14 should be performed whenever there is suspicion of spondyloepiphyseal dysplasia, Ehlers-Danlos syndrome, macular corneal dystrophy and ARMJD, respectively." (PMID 37545696, 2023). "Spondyloepiphyseal dysplasia with congenital joint dislocations, CHST3 type (SEDCJD, MIM 143095), also named recessive Larsen syndrome, is due to biallelic variants in the CHST3 gene, encoding for carbohydrate sulfotransferase-3, also known as chondroitin 6-sulfotransferase 1 (C6ST-1)." (PMID 32295296, 2020). "Disease-causing variants in CHST3, encoding chondroitin 6-sulfotransferase 3 (C6ST), were first identified in patients with spondyloepiphyseal dysplasia (SED), Omani type (OMIM 608637)." (PMID 36042462, 2022).
chondrodysplasia (7 papers, 2015 to 2023). "Human patients with mutations in the chondroitin 6-O-sulfotransferase CHST3 gene develop chondrodysplasia and are diagnosed with Larsen syndrome, although targeted mutations in the Chst3 gene in mice did not result in any apparent phenotype." (PMID 25793894, 2015). "Mutations of CHST3 gene cause skeletal dysplasia, chondrodysplasia, and autosomal recessive multiple joint dislocations while increased tissue expression of CHST11, CHST12 and CHST15 is an unfavourable prognostic factor in ovarian cancer, glioblastoma and pancreatic cancer, respectively." (PMID 37545696, 2023). "Interestingly, a genome-wide association study identified CHST3 as a susceptibility gene for lumbar disc degeneration, and loss-of-function mutation in CHST3 results in chondrodysplasia with major involvement of the spine." (PMID 27252900, 2016). "It is known that a loss of CHST3 function results in human chondrodysplasia." (PMID 26646821, 2015). "In addition, mutation in CHST3 results in chondrodysplasia with major involvement of the spine." (PMID 26646821, 2015). "Loss-of-function mutations in CHST3 are causative of spondyloepiphyseal dysplasia (SED) Omani type (OMIM 143095), in which a missense mutation in CHST3 leads to a generalized defect in the chain sulfation of chondroitin sulfate resulting in severe chondrodysplasia." (PMID 34093655, 2021).
Larsen syndrome (6 papers, 2014 to 2023). A rare skeletal dysplasia characterized by congenital dislocation of large joints, foot deformities, cervical spine dysplasia, scoliosis, spatula-shaped distal phalanges and distinctive craniofacial abnormalities, including cleft palate. "Mutations in CHST3 have been previously associated with short stature, congenital joint dislocations, clubfoot, Larsen syndrome, and elbow joint dysplasia." (PMID 34450027, 2021). "It is important to note that the proportion of cases of Larsen syndrome caused by CHST3 deficiency is currently unknown, but it is believed to be higher than previously thought." (PMID 37565102, 2023). "However, some cases of recessive Larsen syndrome can also be linked to mutations in genes other than FLNB, for example, CHST3 (OMIM:603799)." (PMID 37565102, 2023). "Moreover, missense mutations in the human Carbohydrate sulfotransferase 3 (CHST3) gene, involved in the production of CS, have been shown to be associated with Larsen syndrome, humero-spinal dysostosis, and Omani-type spondyloepiphyseal dysplasia, all of which cause severe skeletal abnormalities." (PMID 24667694, 2014).
lumbar disc degeneration (4 papers, 2016 to 2023). "A genome-wide association study revealed that lumbar disc degeneration is associated with a variant (rs4148941) in the 3′UTR of CHST3." (PMID 36998246, 2023). "CHST3 has also been shown to be associated with lumbar disc degeneration." (PMID 34450027, 2021).
glioma (3 papers, 2018 to 2022). A benign or malignant brain and spinal cord tumor that arises from glial cells (astrocytes, oligodendrocytes, ependymal cells). "For instance, upregulated Chst3 is found in human glioma tissues, where it may enhance cell viability, migration, and invasion of glioma cells." (PMID 35805117, 2022).
emphysema (2 papers, 2015 to 2017). "CHST3 siRNA diminishes accumulation of excessive macrophages and the mediators, leading to accelerate the functional recovery from airway damage by repair of the elastin network associated with pulmonary emphysema." (PMID 26646821, 2015). "Intraperitoneal administration of siRNA targeting CHST3 attenuated lung inflammation, restored the elastin level, and improved lung function and emphysema." (PMID 28106744, 2017). "In the present study to elucidate the role of CHST3 on the development of emphysema, we investigated the effect of siRNA targeting CHST3 on murine emphysema induced by elastase." (PMID 26646821, 2015). "In a murine model of elastase-induced pulmonary emphysema, we found increased carbohydrate sulfotransferase 3 (CHST3), a specific enzyme that synthesizes chondroitin 6-sulfate proteoglycan (C6SPG)." (PMID 26646821, 2015). "To identify the in vivo role of CSPGs in a pulmonary emphysema model, we used the atelocollagen-mediated systemic delivery method for siRNA targeting CHST3." (PMID 26646821, 2015). "In order to elucidate the role of CHST3 in lung inflammation and emphysema, we examined CHST3 expression on days 0, 7 and 21 after PPE-induced lung injury." (PMID 26646821, 2015). "To elucidate the role of C6SPG, we investigated the effect of small interfering RNA (siRNA) targeting CHST3 that inhibits C6SPG-synthesis on the pathogenesis of pulmonary emphysema." (PMID 26646821, 2015). "CHST3 was found elevated in an elastase-induced murine model of pulmonary emphysema." (PMID 28106744, 2017). "CHST3 siRNA breaks this cycle, resulting in amelioration from chronic inflammation to emphysema." (PMID 26646821, 2015). "However, the role of CHST3 in the development of emphysema has not been explored." (PMID 26646821, 2015).
memory impairment (2 papers, 2021 to 2022). "Additionally, there has been strong evidence linking memory impairments in aged mice to Chst3 expression; the deletion of Chst3 resulted in memory loss as early as 11 weeks in mice." (PMID 35805117, 2022). "In mice, deletion of chondroitin 6-sulfotransferase (CHST3) results in an abnormal extracellular matrix in the brain, accelerated brain aging, and memory impairments." (PMID 35821992, 2021).
Omani-type spondyloepiphyseal dysplasia (2 papers, 2014 to 2020). "Interestingly, missense mutations in the human Carbohydrate sulfotransferase 3 (CHST3) gene have been shown to be associated with Omani-type spondyloepiphyseal dysplasia." (PMID 24667694, 2014).
osteoarthritis (2 papers, 2021 to 2022). A noninflammatory degenerative joint disease occurring chiefly in older persons, characterized by degeneration of the articular cartilage, hypertrophy of bone at the margins and changes in the synovial membrane. "Finally, the carbohydrate sulfotransferase 3 agonist thalidomide has been shown to attenuate early osteoarthritis development in a mouse medial meniscus destabilization model through a mechanism involving the downregulation of vascular endothelial growth factor (VEGF) expression." (PMID 34450027, 2021). "Within tier 1, ten candidates have previously been studied in clinical trials of efficacy or in cohort studies of osteoarthritis (six arising from new signals: PPARD, NR3C1, VDR, MAPK14, IGF1R, and CHST3)." (PMID 34450027, 2021). "CHST3, SMAD3, and GDF5 accrued the highest levels of confidence, each with 6 different lines of evidence in support of their involvement in osteoarthritis." (PMID 34450027, 2021).
colon cancer (1 paper, 2020). "Overexpression of CHST3 and CHST11 have been linked to BC aggressiveness, relapse, and development of metastasis; in contrast, downregulation of CHST10 and CHST14 has been linked to invasive melanoma and to late stages of colon cancer progression, respectively." (PMID 32605588, 2020).
disc degeneration (1 paper, 2022). "The analysis that identified CHST3 as a candidate gene in disc degeneration involved a total of 32,642 human subjects of Southern Chinese descent, with 4,083 individuals with lumbar disc degeneration and 28,599 controls." (PMID 35359439, 2022). "Human GWAS meta-analyses have found novel candidate genes that, when mutated, may be associated with disc degeneration, including PARK2 and CHST3." (PMID 35359439, 2022).
hearing loss (1 paper, 2022). "Similarly, a variable degree of hearing loss has also been observed in some other reported SED patients with CHST3 variants but with phenotypic variability among individuals harboring the same CHST3 allele." (PMID 36042462, 2022).
intervertebral disc degeneration (1 paper, 2021). "In this study, we performed bioinformatic analysis of GSE15227 database using grade II, III and IV intervertebral disc degeneration, and we choose CHST3 and CSPG4 as the main targets in the following investigation." (PMID 33993645, 2021). "Then, the exact molecular mechanisms of CHST3 overexpression in CESCs to repair intervertebral disc degeneration by rat nucleus pulposus was explored one by one." (PMID 33993645, 2021). "However, the underlying molecular mechanisms of CHST3 and CSPG4 in CESCs of intervertebral disc degeneration remain unresolved and needs further investigation." (PMID 33993645, 2021). "Co‐IP analysis demonstrated that there was an interaction between CHST3 and CSPG4 in the tissues of intervertebral disc degeneration." (PMID 33993645, 2021). "This phenomenon demonstrated that the differential expression of CHST3 and CSPG4 interacted with each other and their low expression contributed to the pathogenesis of grade II, III and IV intervertebral disc degeneration." (PMID 33993645, 2021). "CHST3 overexpression promoted CESCs to regulate bone marrow cells through interaction with CSPG4 to repair the grade II, III and IV intervertebral disc degeneration." (PMID 33993645, 2021). "We performed GO and KEGG analysis of GSE15227 database to select the differential genes CHST3 and CSPG4 in grade II, III and IV intervertebral disc degeneration, IHC and WB to detect the protein profile of CHST3 and CSPG4, Co‐IP for the interaction between CHST3 and CSPG4." (PMID 33993645, 2021). "Bioinformatic analysis of GSE15227 database shows the differential gene expression of CHST3 and CSPG4 in grade II, III and IV intervertebral disc degeneration, and bioinformatics also predict the relationship between the differentially expressed CHST3 and the protein CSPG4." (PMID 33993645, 2021).
laryngeal carcinoma (1 paper, 2010). Carcinoma that arises from the laryngeal epithelium. "In our study, the most clear observations in laryngeal cancer were the significant decrease of CHSY3, CHST3 and D4ST1, and the significant increase of DSE." (PMID 20929582, 2010).
peripheral nerve injury (1 paper, 2021). Injury to a peripheral nerve. "After axotomy of nigrostriatal axons, Chst3-deficient mice exhibited fewer regenerating axons and more axonal retraction than wild-type mice, although repair of the median and ulnar nerves was similar between wild-type and Chst3-deficient mice after peripheral nerve injury." (PMID 34901009, 2021).
cancer (4 papers, 2010 to 2024). A tumor composed of atypical neoplastic, often pleomorphic cells that invade other tissues. "We were unable to demonstrate clear functions for CHST1 as well as CHST3 in 6-O-sulfation of the cancer-associated Tn O-glycan." (PMID 34954141, 2022). "According to our study CHST3 gene expression was decreased in cancer compared to healthy tissues profoundly leading to C-6 sulfation decrease." (PMID 20929582, 2010). "In a previous study, we demonstrated that CHST3 and D4ST1 were expressed differentially in colorectal cancer, thus leading to increased C-6 sulfation in cancer compared to healthy tissues and decreased C-4 sulfation in late stages." (PMID 20929582, 2010).
tumor (4 papers, 2013 to 2022). "Inmunohistochemical studies were performed for CHST3 using specific antibodies; these analyses allowed us to visualize the decrease in immunostaining as tumor cell proliferate in relation to healthy tissue." (PMID 23327652, 2013).
skeletal dysplasia (2 papers, 2023 to 2024). Any Mendelian diseases that affects growth and development of the skeleton. "Mutations in CHST3 lead to skeletal dysplasia, highlighting the important function of this protein in skeletogenesis." (PMID 39579763, 2024).
Mendelian diseases (1 paper, 2023). "A number of potential OA GWAS effector genes have been identified, including some that have been implicated in Mendelian diseases with joint and skeletal abnormalities, such as BICRA (also known as GLTSCR1), EIF6, CHST3, and FBN2." (PMID 37579195, 2023).
CHST3 also shares sentences with these, for which no sentence is quoted: ovarian carcinoma (2 papers); acute promyelocytic leukemia (1); Allergy (1); Arthrochalasia EDS (1); asthma (1); autosomal recessive inherited disease (1); colorectal cancer (1); dislocation (1); dysplasia (1); Ehlers-Danlos syndrome (1); epilepsy (1); Erythema (1); glioblastoma (1); hypertrophy (1); Kyphoscoliosis (1); Kyphoscoliotic EDS (1); macular corneal dystrophy (1); melanoma (1); memory (1); Microdontia (1); Musculocontractural EDS (1); narcolepsy (1); pancreatic cancer (1); Periodontal EDS (1); pituitary adenomas (1); postural orthostatic tachycardia syndrome (1); psoriasis (1); Vascular EDS (1).